SPDYE13 (speedy/RINGO cell cycle regulator family member E13)
Synonyms: SPDYE13P
Gene: Protein-coding gene on chromosome 7 (75,280,790 to 75,289,501, forward strand). Ensembl gene ENSG00000286038.
Gene Ontology:
Molecular function: protein kinase binding
Homologues: Orthologues: rat Spdye4 (49% identical), mouse Spdye4a (48% identical), mouse Spdye4b (44% identical). Paralogues in human: SPDYE14 (100% identical), SPDYE15 (100% identical), SPDYE10 (99% identical), SPDYE11 (99% identical), SPDYE17 (99% identical), SPDYE8 (99% identical), SPDYE9 (99% identical), SPDYE12 (99% identical), SPDYE3 (88% identical), SPDYE18 (84% identical), SPDYE16 (83% identical), SPDYE2 (83% identical), and 6 more.